SLC38A2 (solute carrier family 38 member 2)
Diseases named in the same sentence as SLC38A2 in open-access papers (continued):
Sharing a sentence is not in itself a finding about the gene and the disease.
tumor (continued). "IHC analysis revealed that PHGDH, SLC1A5 and SLC38A2 are expressed in the GCs of TLSs in both normal and tumour colorectal tissues, suggesting that serine metabolism might play a critical role in GC formation." (PMID 40660426, 2025). "However, tumor cells compete with cDC1s for glutamine in the tumor microenvironment via the SLC38A2 transporter, thus impeding cDC1 function and evading T cell-mediated killing." (PMID 39905317, 2025). "Furthermore, SLC38A2 is positively correlated with tumor and stromal cells, negatively correlated with immune cell infiltration, and associated with immune exhaustion." (PMID 41040664, 2025). "Moreover, high SLC38A2 expression in tumor cells restricts glutamine uptake by cDC1s, highlighting glutamine uptake via SLC38A2 as a checkpoint in dictating cDC1-tumor crosstalk." (PMID 38213515, 2024). "Notably, we establish that SLC38A2 expression in tumour cells and cDC1s has reciprocal effects on tumour growth, establishing SLC38A2-mediated glutamine acquisition as an intercellular metabolic checkpoint for controlling anti-tumour immunity." (PMID 37407815, 2023). "However, intratumoral glutamine supplementation had little effect on MC38 tumour growth in Slc38a2ΔDC mice, indicating a functional link between glutamine and SLC38A2 expressed by DCs in anti-tumour immunity." (PMID 37407815, 2023). "Mechanistically, SLC38A2 deficiency did not impair antigen uptake or the migratory capacity of DCs, nor their functionality to induce naive T cell priming in tumour dLNs." (PMID 37407815, 2023). "The results demonstrated that the infiltration of CD8 + T cells, macrophages, myeloid dendritic cells, neutrophils and natural killer cells were positively correlated with SLC38A2 expression, suggesting the importance of SLC38A2 in regulating GC tumour immunity." (PMID 36918802, 2023). "Tumour cells expressed higher Slc38a2 transcript levels than DCs, CD8+ T or other immune cells." (PMID 37407815, 2023). "The role of SLC38A2 in tumor immune infiltration was explored using the TIMER database." (PMID 36918802, 2023). "Furthermore, enrichment analysis of SLC38A2 in GC was performed, and the correlation between SLC38A2 and tumor-infiltrating immune cells was analyzed." (PMID 36918802, 2023). "Thus, SLC38A2 represents a putative intercellular metabolic checkpoint for dictating glutamine uptake and downstream functions between tumour cells and cDC1s." (PMID 37407815, 2023). "SLC38A2 transcripts were highly expressed in both mouse and human tumour cells." (PMID 37407815, 2023). "In addition, the levels of LINC01614 in primary CAFs positively associated with the mRNA levels of SLC38A2 and SLC7A5 in the paired LUAD tumor cells." (PMID 36209111, 2022). "Furthermore, we correlated LINC01614 expression with tumor glutamine transporters, as detected by immunostaining for SLC38A2 and SLC7A5 and CAF infiltration as denoted by α-SMA immunostaining in 10 cases of patients with LUAD." (PMID 36209111, 2022). "Moreover, tumours with high SLC38A2 expression were also commonly represented in the poor prognostic high SLC cluster (SLC1A5+/SLC7A5+/SLC3A2+)." (PMID 33028955, 2021). "Interestingly, alanine uptake via SLC38A2 supports tumour cells clonogenic and tumour-initiating potential even in nutrient-rich conditions, highlighting another vulnerability of PDAC cells with enhanced tumourigenic potential." (PMID 34588983, 2021). "Finally, to examine whether cDC1-specific expression of SLC38A2 is sufficient to control tumour growth, we generated Xcr1cre/+Slc38a2fl/fl mice to delete SLC38A2 specifically in cDC1s38." (PMID 37407815, 2023). "Notably, similar to FLCN deficiency, SLC38A2 deficiency in DCs eliminates the anti-tumour effect of glutamine supplementation, thereby establishing this glutamine transporter and FLCN signalling as critical drivers of cDC1 function and tumour immunity." (PMID 37407815, 2023).
tumor (continued). "In addition, both QRT-PCR and immunofluorescence confirmed that circ_001859 could regulate tumor epithelial-mesenchymal transition (EMT) through the miR-21-5p/SLC38A2 pathway." (PMID 37005877, 2023). "Glutamine, a key nitrogen and energy donor for tumor cells, is imported into the cytoplasm via the transporters SLC1A5, SLC38A1, and SLC38A2." (PMID 41041303, 2025). "This reprograms glutamine metabolism by upregulating transporters solute carrier family 38 member 2 (SLC38A2) and solute carrier family 7 member 5 (SLC7A5), boosting glutamine uptake to fuel tumor growth." (PMID 41409273, 2025). "The glutamine/SLC38A2/FLCN axis potently orchestrates cDC1-mediated coordination of CD8+ T cell accumulation and function in promoting anti-tumor immunity." (PMID 38213515, 2024). "Subsequently, the results of RT-qPCR experiments demonstrated that the mRNA expression levels of SLC38A2, SLC38A3 and SLC38A4 were significantly overexpressed in GC tumor tissues." (PMID 36918802, 2023). "By analyzing TCGA data in the GEPIA database, we found that the expression levels of multiple SLC38A family members (including SLC38A2, SLC38A4, SLC38A5, SLC38A6, SLC38A7, SLC38A8, SLC38A9, and SLC38A10) were significantly upregulated in GC tumor tissues." (PMID 36918802, 2023). "Consistently, LINC01614 was abundant in CAFs, and LINC01614 expression of tumor cells was positively correlated with the density of α-SMA+ CAFs and the expression of SLC38A2 and SLC7A5 in tumors." (PMID 36209111, 2022). "SLC38A2, DUSP1, and FGF7 expressed predominantly in tumor sites than that in normal lung in previous studies; however, they were expressed predominantly in the tumor stroma in this study." (PMID 36505794, 2022). "Most genes considered tumor specific in previous studies (tumor suppressor genes: SOCA3, KLF6, and PTGDS; tumor enhancer genes: SLC38A2, DUSP1, and FGF7) were expressed predominantly in tumor stroma or remission stroma than that in pre-treatment tumors." (PMID 36505794, 2022). "Both low and high proliferative luminal tumours showed weak positive correlation between GLS2 protein and ALDH18A1 (p < 0.001), ALDH4A1 (p < 0.01), ATF4 (p = 0.001), PRODH (p < 0.001), SLC38A2 (p ≤ 0.001) and SLC7A11 (p < 0.001)." (PMID 34439127, 2021). "With respect to the luminal subtypes, both luminal A (low proliferative) and B (high proliferative) tumours showed a weak positive correlation between GLS mRNA and protein expression with GLUD1 and SLC38A2 (p < 0.01)." (PMID 34439127, 2021). "Further studies showed that this paracrine–alanine network was dependent on specific transporters, SLC38A2 on the cancer cells and SLC1A4 on the CAFs, and targeting SLC38A2 was sufficient to impede tumor growth." (PMID 34948209, 2021). "SLC1A4 and SLC38A2 (alanine transporter) and SLC1A5 (ASCT2-glutamine transporter) enhance PDAC tumor growth by importing essential amino acids and therefore represent additional potential therapeutic targets." (PMID 33198082, 2020). "Cells lacking SLC38A2 fail to concentrate intracellular alanine and undergo a profound metabolic crisis resulting in markedly impaired tumor growth." (PMID 40688069, 2025). "The overexpression of SLC38A2 enhances the nutritional tug-of-war between tumor cells and immune cells, inhibiting the activity of effector T cells (CD8+ T cells) while increasing the abundance of tumor-promoting Th2 cells." (PMID 41040664, 2025). "SLC38A2, an amino acid transporter widely expressed on the surface of tumor cells, has not been thoroughly studied regarding its function and prognostic significance in tumor progression." (PMID 41040664, 2025). "In conclusion, we propose that Slc38a2 is likely a pivotal gene that mediates the activation of Mig cDC1s after combined treatment, drives the differentiation of TTSM and TPEX cells, and thereby enhances anti‐tumor immune responses." (PMID 39629989, 2025).
tumor (continued). "In contrast, although SLC1A5 and SLC38A2 showed statistically significant differences in certain datasets, their expression levels between normal intestinal epithelium and tumour cells were not markedly distinct." (PMID 40660426, 2025). "Both tumor cells and cDC1s engage in competitive uptake of glutamine through the SLC38A2 transporter protein, and the lack of SLC38A2 compromises the ability of DCs to promote T cell priming." (PMID 38459595, 2024). "By contrast, sgRNA-mediated deletion of Slc38a2 in Cas9-expressing OT-I cells did not impair their ability to control B16-OVA tumour growth." (PMID 37407815, 2023). "Accordingly, abundance of glutamine, but not other SLC38A2 substrates, was increased in TIF from SLC38A2-deficient B16-OVA tumours, further supporting that SLC38A2 more selectively mediates the transport of glutamine." (PMID 37407815, 2023). "Thus, DCs but not T cells require SLC38A2 to orchestrate anti-tumour immunity, suggesting that SLC38A2 represents a competitive checkpoint between tumour cells and cDC1s for glutamine acquisition and tumour–immune interactions." (PMID 37407815, 2023). "However, a lack of anti-tumour effect in spheroids was seen in the Gln-sensitive cell MDA-MB-231 cell line in response to SLC38A2 inhibition." (PMID 33028955, 2021).
cancer (44 papers, 2017 to 2026). A tumor composed of atypical neoplastic, often pleomorphic cells that invade other tissues. "The GO enrichment analysis indicates that SLC38A2 is primarily associated with the following pathways in cancer." (PMID 41040664, 2025). "For instance, SLC38A2, which encodes a glutamine transporter, plays a critical role in sustaining cancer cell proliferation, survival, and migration." (PMID 41154614, 2025). "Although these findings suggest an association between SLC38A2 and cancer prognosis, TME, and immunity, there are limitations." (PMID 41040664, 2025). "Among all genes analyzed, SLC38A2 emerged as the most consistently ranked and strongly cancer-associated transcript." (PMID 40941703, 2025). "To further elucidate glutamine metabolism in pan-cancer and analyze its association with SLC38A2, we conducted further validation in COAD and LUAD." (PMID 41040664, 2025). "The mutation analysis results indicate that the main types of mutations for SLC38A2 in cancer are amplification, mutation, and deep deletion." (PMID 41040664, 2025). "We found that SLC38A2 is expressed at higher levels in younger patients with certain cancers, potentially indicating increased risk." (PMID 41040664, 2025). "Together, these data show that SMARCA4/2-deficient cancer cells depend on elevated SLC38A2 for glutamine uptake and metabolism to sustain the TCA cycle." (PMID 37210563, 2023). "The sodium-coupled neutral amino acid transporter 2 (SNAT2, SLC38A2) has been implicated in cancer for its ability to supply cancer cells with glutamine and sarcosine." (PMID 38239202, 2023). "Additionally, diagnostic ROC and time-dependent AUC results demonstrate that SLC38A2 is indeed a reliable diagnostic marker in some cancers, further supporting its clinical application potential." (PMID 41040664, 2025). "Interestingly, we found that SLC38A2 acts as a protective factor in certain cancers, particularly KIRC, where it is linked to favorable prognosis." (PMID 41040664, 2025). "Given the established biological functions of SLC38A2, we hypothesized that it is a risk factor for cancer prognosis." (PMID 41040664, 2025). "Additionally, the results of the multivariate Cox regression further confirmed that SLC38A2 acts as an independent risk factor in these cancers." (PMID 41040664, 2025). "Together, these data demonstrate that alanine could be used to target glutamine dependency in SMARCA4/2-deficient cancer cells by suppressing SLC38A2-mediated glutamine import and consequently, inhibiting glutaminolysis and OXPHOS." (PMID 37210563, 2023). "Recent research has focused on the role of SLC38A2 in metabolic reprogramming and its connection to cancer progression." (PMID 41040664, 2025). "Transporter SLC38A2 represents one of the major promoters of glutamine entry into cells under physiological conditions and is frequently overexpressed in cancer cells." (PMID 39875724, 2025). "The analysis results from the ssGSEA algorithm indicate that the expression of SLC38A2 is generally negatively correlated with immune cells in most cancers." (PMID 41040664, 2025). "Addintionally, several studies underscore the pivotal role of SLC38A2 in the clinical outcomes of various cancers." (PMID 41040664, 2025). "We found that SLC38A2 expression was higher in younger patients, especially in six types of cancer: ESCA, KIRC, PAAD, READ, TGCT, and THCA." (PMID 41040664, 2025). "Specifically, SLC38A2 is overexpressed in eight types of cancer which include BLCA (p < 0.05), COAD (p < 0.001), ESCA (p < 0.05), HNSC (p < 0.001), KIRC (p < 0.001), KIRP (p < 0.05), LUSC (p < 0.001), and STAD (p < 0.001)." (PMID 41040664, 2025). "Further analysis was conducted on the correlation between SLC38A2 and infiltrating immune cells in four types of cancer which include BRCA, LUAD, MESO, and PAAD." (PMID 41040664, 2025).
cancer (continued). "Unlike what we observed in murine HCC, SLC38A1 was globally expressed in all human cancer cells, alongside SLC38A2 being the most highly expressed glutamine transporter in all studied HCC cells." (PMID 39062801, 2024). "Previous studies have reported the upregulation of SLC38A2 in cancer cells with knock-down of the SLC38A1 gene, indicating a possible compensatory functional overlap between SLC38 protein members." (PMID 38254895, 2024). "The sodium-coupled neutral amino acid transporter SNAT2 (SLC38A2) has been shown to have important physiological functions and is implicated in various diseases like cancer." (PMID 39427053, 2024). "We tested the effect of CB6644 (targeting RUVBL1/2 complex), MKT077 (inhibiting HSPA9), selinexor (blocking XPO1, nuclear exportin), and MeAIB (targeting SLC38A2) on cell lines representing three different cancer types versus the normal fibroblasts." (PMID 39217152, 2024). "Remarkably, the SLC38A2 expression level has been found to be significantly higher in poorly differentiated than in well differentiated cancer tissues." (PMID 36918802, 2023). "Supporting that alanine supplementation competes with glutamine for SLC38A2, the addition of glutamine or ectopic expression of SLC38A2 rescued SMARCA4/2-deficient cancer cells from growth suppression and OXPHOS inhibition caused by alanine treatment." (PMID 37210563, 2023). "Previous studies have reported that abnormal SLC38A2 expression can induce cancer-like metabolic characteristics and promote breast and pancreatic cancer." (PMID 36918802, 2023). "Among them, ASCT2 (SLC1A5), SNAT1 (SLC38A1) and SNAT2 (SLC38A2) play a major role in cancer cells, since ASCT2 is required for optimal growth at low glutamine concentrations, whereas SNAT1 and SNAT2 mainly mediate net glutamine uptake for glutaminolysis." (PMID 36768660, 2023). "Therefore, the long-term effects of alanine supplementation require further investigation for patients with SMARCA4/2-deficient cancers along with the development of SLC38A2 inhibitors, that may also prove efficacious for other SLC38A2-dependent tumors such as pancreatic cancer." (PMID 37210563, 2023). "Due to its transmembrane localisation and the vulnerability of the TNBC cell lines to Gln depletion and SLC38A2 knockdown, SLC38A2 is potentially a useful target for this cancer subtype." (PMID 33028955, 2021). "Collectively, our data reveal that oncogenic KRAS alters the expression of AATs such as SLC1A5/ASCT2, SLC7A5/LAT1, and SLC38A2/SNAT2 and thereby increase the uptake of AAs to support cancer cell proliferation through mTOR activation." (PMID 34003553, 2021). "On the other hand, V‐9302 has been shown to strongly reduce cancer cell proliferation with combined inhibition of SLC38A2/SNAT2‐ and SLC7A5/LAT1‐mediated amino acid transport." (PMID 34003553, 2021). "For example, the alanine–serine–cysteine transporter 2 (ASCT2), otherwise known as SLC1A5, and SLC38A2 (SNAT2), are the primary transporters responsible for glutamine uptake in cancer cells." (PMID 34541580, 2021). "Additionally, the expression of SLC38A2 in lung, breast, and oral epithelial tissues, as well as their corresponding cancers (LUAD, BRCA and HNSC) were also examined." (PMID 41040664, 2025). "In paired sample analysis, SLC38A2 shows differential expressions in 10 types of cancer, including BLCA (p < 0.01), COAD (p < 0.01), HNSC (p < 0.001), KIRC (p < 0.001), KIRP (p < 0.05), LUSC (p < 0.001), BRCA (p < 0.05), LIHC (p < 0.001), THCA (p < 0.001), and UCEC (p < 0.001)." (PMID 41040664, 2025). "To verify whether the expression of SLC38A2 is abnormal in cancer, we first conducted differential expression analysis across 33 common cancer types in the TCGA database." (PMID 41040664, 2025). "Additionally, the WGCNA results further demonstrate the role of the glutamine metabolic pathway in certain malignant tumors and emphasize its inseparable connection with SLC38A2." (PMID 41040664, 2025).